FGFR2 (fibroblast growth factor receptor 2)
Diseases named in the same sentence as FGFR2 in open-access papers (continued):
Sharing a sentence is not in itself a finding about the gene and the disease.
breast carcinoma (continued). "Pools of S115 mouse breast cancer cells expressing shRNA against FGFR1, 2 and 3 were created by lentiviral gene transfer, resulting in cells with downregulated expression of FGFR1, FGFR2 or FGFR3 (shR1, shR2 and shR3 cells, respectively) and shLacZ controls." (PMID 23185502, 2012). "To further study this finding, we silenced FGFR2 and FGFR3 using shRNA lentiviral particles in the mouse breast cancer cell line 4T1." (PMID 23185502, 2012). "Variable nuclear staining for FGFR2 in breast cancer, but an absence of correlation with rs2981582 genotype suggests that the mechanism of action of polymorphisms at the FGFR2 locus may be more complex than a direct effect on mRNA expression levels in the final cancer." (PMID 21418638, 2011). "Further analysis has shown that allelic variation at FGFR2, TNRC9, 8q24, 2q35, and 5p12 is associated with physiological characteristics of breast tumors, such as ER status, and specific FGFR2, MAP3K1, and TNRC9 variants may interact with BRCA1 and BRCA2 mutations to increase breast cancer risk." (PMID 21037853, 2010). "Meanwhile, epigenetic silencing caused by methylation was previously observed for at least five ASE genes identified in our study, including DSC3, FGFR2 and MGMT in breast cancer and/or in other cancer types." (PMID 21108794, 2010). "Increased levels of FGF10 are observed in ~10% of human breast cancers, and amplification and overexpression of several FGFRs, including FGFR1, FGFR2, and FGFR4, have been observed in breast cancers." (PMID 16933995, 2006). "For examples, the insertions cause heamophilia B (factor IX gene), neurofibromatosis (NF-1 gene), Apert syndrome (FGFR2 gene), acholinesterasemia (ChE gene), desmoid tumors (APC gene) and breast cancer (see the review by Kazazian, 1998)." (PMID 12610505, 2003). "While our in vivo data highlight the plasticity of Fgfr2-mutant HP5008 and Brca1-mutant 545 cells, further investigations using additional ERα+ cell lines are warranted to determine if this phenotypic shift is a common feature of ERα+ breast cancers." (PMID 41318657, 2025). "The FGFR2 rs2981578 G/A genotypes and behavioral characteristics in breast cancer patients and non-cancer controls." (PMID 40748883, 2025). "The FGFR2 rs2981578 G/A genotypes and reproductive characteristics in breast cancer patients and non-cancer controls." (PMID 40748883, 2025). "Notably, 1 (12.5%) of 8 breast cancer patients with FGFR1 amplification and 3 (33.3%) of 9 gastroesophageal cancer patients with FGFR2 amplification had confirmed responses with AZD4547." (PMID 37980453, 2023). "We previously identified that the downregulation of Pleckstrin Homology-Like Domain family A member 1 (PHLDA1) underpins resistance to receptor tyrosine kinase (RTK)-targeted therapy in both fibroblast growth factor receptor 2 (FGFR2)-mutant endometrial and HER2-amplified breast cancers." (PMID 37047202, 2023). "Then, FGFR2 activated HER2 through c-Src, leading to resistance of HER2 targeted therapies, considering the TAF/FGF5/FGFR2/c-Src/HER2 axis was the escape pathway of HER2 targeted therapy resistance in breast cancer." (PMID 37174034, 2023). "Lucitanib strongly inhibits FGFR1, FGFR2, and VEGFR1–3, and it has antiangiogenic and broad‐spectrum antitumor activity against several cancers, including small cell lung cancer, breast cancer, nasopharyngeal carcinoma, colorectal cancer, ovarian cancer, and kidney cancer." (PMID 37750089, 2023). "Although FGFR1 is amplified more often in breast cancer, both FGFR1 and FGFR2 amplified and overexpressing breast cancers could likewise benefit from AZD4547 treatment." (PMID 37805590, 2023).
breast carcinoma (continued). "Indeed, breast cancers with any degree of HER2 amplification appear to demonstrate sensitivity to HER2 targeted therapy; however, much higher levels of HER2 or FGFR2 expression are required before effective therapeutic targeting is seen in gastric cancer." (PMID 35448150, 2022). "In ER+ breast cancer cells, the effect of TAM is diminished by activation of the FGFR2 signaling." (PMID 36601474, 2022). "We also analyzed the relationship between the mRNA levels of FGFR2, ERBB4, RET, FN1, MMP16, and SOX2 and tumor stages in breast cancer using GEPIA and found that the levels of FGFR2 were significantly upregulated in stage I and remained stable across stages II–X." (PMID 36601474, 2022). "While the significance of these alternate forms of FGFR2 is not clear, nuclear forms of the receptor have been described previously in bone, prostate, and breast cancer suggesting a novel role for this receptor, which requires investigation." (PMID 34850536, 2022). "Given the complex regulation of the FGFR2 gene it is not surprising that FGFR2-dependent signalling is deregulated in breast cancer." (PMID 35193394, 2022). "In addition to the FGF3 locus (int-2 in mice), high-throughput analysis of the MMTV insertional mutagenesis identified an activated FGF pathway in 67% of the mammary tumors with virus common insertion sites near FGFR1 and FGFR2." (PMID 35996584, 2022). "Along this line, we have recently showed that FGFR2-IgIIIb and EGFR engage in reciprocal regulation of each other’s signaling and trafficking in breast cancer cells, confirming that FGFR trafficking regulation may become a target for therapeutic intervention." (PMID 34068954, 2021). "Our data highlighting effective targeting of oncogenic FGFR2 and FGFR4 alterations in specific PDX led us to analyze the METABRIC and TCGA datasets using cBioPortal to determine the frequency of FGFR2 and FGFR4 genomic and expression changes in different breast cancer subtypes." (PMID 34344433, 2021). "The PsePDC-DTIs model provides us with 10 potential DTIs for breast cancer treatment, among which erlotinib (DB00530) and FGFR2 (hsa2263), caffeine (DB00201) and KCNN4 (hsa3783), as well as afatinib (DB08916) and FGFR2 (hsa2263) are found with direct or inferred evidence." (PMID 34946556, 2021). "Treatment of ER+ breast cancer cells with FGFR inhibitors AZD4547 and PD173074 sensitized the cells to the anti-estrogen tamoxifen suggesting that targeting FGF10/FGFR2 may be a new approach to overcome resistance to hormone-deprivation therapy." (PMID 34830951, 2021). "In human breast cancer, FGFR2 moves to the nucleus after activation by extracellular ligands; however, the commercial ATP pocket inhibitor PD173074 blocks this agonist-induced FGFR2 nuclear translocation and inhibits RTK activity and downstream pathways." (PMID 33924850, 2021). "Nuclear FGFR2 was recently found to negatively regulate hypoxia-induced cell invasion in prostate cancer and nuclear FGFR1 was positively corelated with pancreatic and breast cancer progression." (PMID 34830836, 2021). "It should be mentioned that, in breast cancer cells, the activation of the FGF7/FGFR2 axis may induce the proteasomal degradation of ER, preventing the inhibitory effects elicited by tamoxifen." (PMID 33081025, 2020). "The FGFR-specific inhibitors NPV-BGJ398, AZD4547 and JNJ-42756493 are under development for treating lung and breast cancers with FGFR1 amplification, gastric cancer with FGFR2 amplification, cholangiocarcinomas with an FGFR2 fusion, and urothelial cancers with FGFR3 alterations." (PMID 31601997, 2019). "FGFR2 is recurrently amplified in 5% of gastric cancers and 1%–4% of breast cancers; however, this molecular alteration has never been reported in a primary colorectal cancer specimen." (PMID 28835367, 2017).
breast carcinoma (continued). "Taken together, our results indicate that FGFR2/RSK2 signalling loop may participate in BCa progression and be predictive of poor outcome in patients with breast carcinoma." (PMID 27476168, 2016). "A primary goal of the experiments reported here was to elucidate complete functional oncogene signatures for a small panel of SUM breast cancer cell lines, each of which is known to harbor a driving RTK oncogene activated by amplification (SUM-52/FGFR2, SUM-185/FGFR3, SUM-225/HER2, SUM-190/HER2)." (PMID 27153554, 2016). "Consistent with this view, we found a single hotspot (p.N549) for FGFR2 in breast cancer in the kinase domain, which had not been reported as a hotspot for breast cancer." (PMID 25794154, 2015). "Fourth, we observed that a ~15-kb HOT region that harbours two SNPs (rs2981578 and rs7895676) was found in FGFR2 intron 2 in breast cancer cells but not normal breast cells." (PMID 26113264, 2015). "Only SNPs in the known breast cancer susceptibility loci FGFR2 and TOX3 were associated with non-TN breast cancer in BRCA2 carriers, and none were associated with TN breast cancer at P <10−6." (PMID 25919761, 2014). "FGFR2 amplification has been described in 5% of gastric cancers and 1–4% of breast cancers, but has not been reported in colon cancer." (PMID 24968263, 2014). "Notably, four C-oncogenes (NOTH1, FGFR2 and MYC for the breast cancer and FGFR3 for the colorectal cancer) were found to be amplified but down-regulated in their corresponding cancer types." (PMID 23472150, 2013). "For molecular imaging strategies, a putative panel consisting of markers for EGFR, IGF1-R, FGFR2, GLUT1, CAXII, CD44v6 was positive in 77% of cases and might be considered for development of molecular tracers for male breast cancer." (PMID 23308200, 2013). "Four further genes, FGFR2, LSP1, MAP3K1, and TOX3, were associated with a mild increase in risk of breast cancer in a GWAS; however over 50% of breast cancers occur in women who do not carry these higher risk genotypes." (PMID 23738139, 2013). "Expression of IGF1-R, MET, FGFR2, and CD44v6 was not correlated to clinicopathological features in both male and female breast cancer." (PMID 23308200, 2013). "Independent of these roles of FGFR2 in breast cancer, recent studies in mammary gland development revealed that FGFR2 is essential in the maintenance of terminal end buds (TEBs) where mammary stem cells are active during mammary gland development." (PMID 23300950, 2013). "In breast cancer, amplification and/or overexpression of FGFR1, FGFR2 and FGFR4 have been found." (PMID 23185502, 2012). "Our findings, including the nuclear localisation of FGFR2 and the lack of effect of FGFR2 genotype at rs2981582 on cytoplasmic expression, are important findings that show that expression of FGFR2 in breast cancer, and its relationship to genotype is complex." (PMID 21418638, 2011). "Nuclear expression of FGFR2 has been observed previously in normal mouse breast development and lung tumours, as well as mouse mammary gland but not human breast cancer." (PMID 21418638, 2011). "FGFR2 is involved in breast development, so increased FGFR2 expression may be an early event in embryonic development or childhood that sets the scene for a higher risk of breast cancer in later life without being involved directly in tumour behaviour in the adult." (PMID 21418638, 2011). "Notably, gefitinib treatment also induces FGFR2 protein in MCF-7 cells, a breast cancer cell line, and 3 different head and neck cancer cell lines (UMSCC2, UMSCC8, and HN31)." (PMID 21152424, 2010). "One-third of these loci affected breast cancer oncogenes, whose amplifications were validated with specific probes: 17q12 (two cell lines with ERBB2 amplifications), 11q13 (two with cyclin-D1), 8p11–p12 (two with FGFR1) and 10q25 (one with FGFR2)." (PMID 10604729, 1999). "Indeed, FGFR2 therapy in ER-positive HER2 negative breast cancer is being considered as an alternative to failing endocrine therapy." (PMID 39596875, 2024).
breast carcinoma (continued). "We also have analyzed 60 breast cancer samples by immunohistochemistry (IHC) and found FGFR2 is negatively correlated with YY1 and BRCA1, suggesting that YY1 could be responsible for BRCA1 reduction in response to FGFR2 activation." (PMID 34514747, 2021). "However, there are reports showing that FGF2/FGFR2 protein level in glioma and breast cancer tissue does not differ from that in non-malignant parental cells, or is even lower." (PMID 34830951, 2021). "Various meta-analysis studies have been conducted and reported that SNP FGFR2 rs2981582 TT is linked to an increased risk of BC, but until now the exact mechanism of carcinogenesis linking SNP FGFR2 rs2981582 TT to BC, especially early breast cancer onset has not been found." (PMID 31759353, 2019). "There are, to date, no studies of FGFR2 expression in mammary neoplasms in the canine species." (PMID 28945747, 2017). "Therefore a panel composed of IGF-1R, CD44v6, GLUT1, CAXII, FGFR2, and EGFR might be suitable for molecular imaging of male breast cancer." (PMID 23308200, 2013). "Using both parental and shBrca1 knockdown MDA-MB-231 cells, we demonstrated that overexpression of FGFR2 could dramatically promote tumor cell growth and activate downstream targets, illustrating the oncogenic role of FGFR2 and its related signaling in breast cancers regardless of BRCA1 status." (PMID 37063417, 2023). "Furthermore, the authors showed that FGF5 secreted by cancer-associated fibroblasts (CAF) in the microenvironment might be responsible for the high activation of FGFR2 on the neighbouring epithelial cells, confirming the potential signalling switch between HER2 and FGFR2 in breast cancer." (PMID 35193394, 2022). "Since Runx2 directly regulated Fgfr2 and the knockdown of Fgfr2 was effective for inhibiting the proliferation of osteoblast progenitors, the regulation of FGFR2 by RUNX2 may also play an important role in the development and progression of some breast cancers by enhancing cell proliferation." (PMID 30202094, 2018). "For example, the fibroblast growth factor receptor FGFR2 protein highly correlates with RNA in endometrial cancer (Endo) and LUSC, but not in breast cancer (BRCA) and ovarian cancer." (PMID 37290530, 2023). "The genes FGFR2, CCND1 and TOX3 are still not studied much in relation to the roles in breast cancer although genetic studies have suggested their involvement in cancer risk." (PMID 35267517, 2022). "In contrast, FGFR2 and FGFR3 were not significantly correlated with any subgroup of breast cancer cell lines, whereas FGFR4 expression was elevated in HER2 and luminal cell lines." (PMID 33772015, 2021). "In preclinical studies, dovitinib showed the ability to inhibit FGFR1‐ and FGFR2‐amplified, but not FGFR‐normal breast cancer cell lines in vitro and inhibit tumour growth in FGFR1‐amplified breast cancer in vivo." (PMID 33655556, 2021). "When endogenous TGF-β was inhibited by a TGF-β receptor inhibitor, FGFR isoform switching and the regulation of FGFR1 and FGFR2 mRNA were not significantly altered in OSCC cells, in agreement with our previous observation in breast cancer cells." (PMID 31682640, 2019). "Expression levels of FGFR2 and RSK2 assessed independently have been reported in several studies as negative prognostic factors for patients with breast carcinoma." (PMID 27476168, 2016). "We have recently demonstrated that both FGFR2 and RSK2 were expressed in primary breast cancer samples and lack of combined immunoreactivity for FGFR2 and activated RSK (RSK-P) was predictive of a better patients’ disease-free survival." (PMID 27852068, 2016). "We also performed MLPA analysis to detect copy number variations in FGFR2 and FGF10 in sporadic breast cancer patients but did not identify any copy number changes in either of the two genes." (PMID 23527311, 2013).
breast carcinoma (continued). "FGF7, also secreted by breast fibroblasts, has similarly been suggested to act as a paracrine growth factor in human breast cancer, but our data do not demonstrate a significant link between FGF7 and FGFR2 expression." (PMID 21767389, 2011). "On the other hand, some reports suggest that variation in FGFR2, TOX3, HCN1, and at 2q35 may be more strongly associated with estrogen receptor-positive cancers, but mammographic density has not been found to be differentially related to breast cancers by steroid receptor status." (PMID 19232126, 2009). "We also treated mouse 4T1 breast cancer cells with shRNA lentiviral particles targeting FGFR1-3.The silencing efficiency was not as high as in S115 cells, but nevertheless FGFR2 and FGFR3 silencing also resulted in increased FGFR1 gene expression in these cells." (PMID 23185502, 2012).